GFUS (GDP-L-fucose synthase)
Description:
Catalyzes the two-step NADP-dependent conversion of GDP-4-dehydro-6-deoxy-D-mannose to GDP-fucose, involving an epimerase and a reductase reaction.
Synonyms: SDR4E1; TSTA3; FX; P35B
Tractability: Small molecule: a structure with a bound ligand is known. PROTAC: ubiquitination databases record sites on it.
Gene: Protein-coding gene on chromosome 8 (143,612,617 to 143,618,048, reverse strand). Ensembl gene ENSG00000104522.
Subcellular location (Human Protein Atlas): Cytosol; Nucleoplasm
Pathways (Reactome):
Metabolism of proteins: GDP-fucose biosynthesis
Gene Ontology:
Molecular function: GDP-L-fucose synthase activity; GDP-mannose 3,5-epimerase activity; identical protein binding; protein binding; electron transfer activity; GDP-4-dehydro-D-rhamnose reductase activity; isomerase activity; oxidoreductase activity
Biological process: 'de novo' GDP-L-fucose biosynthetic process; GDP-mannose metabolic process; positive regulation of endothelial cell migration; positive regulation of endothelial cell-matrix adhesion; leukocyte cell-cell adhesion; nucleotide-sugar biosynthetic process
Cellular component: cytosol; extracellular exosome
Genetic constraint (gnomAD): Loss-of-function variants: 42 observed, 41.49 expected, observed/expected ratio (o/e) 1.01, 90% interval 0.79 to 1.31. The upper end of that interval is the gene's LOEUF score, 1.31, which puts it in group 5 of 6, group 1 being the genes least tolerant of losing a copy. Missense variants: 437 observed, 443.05 expected, observed/expected ratio (o/e) 0.99, 90% interval 0.91 to 1.07. Synonymous variants: 188 observed, 179.56 expected, observed/expected ratio (o/e) 1.05, 90% interval 0.93 to 1.18.
Gene-disease validity (ClinGen):
ClinGen rates the evidence that GFUS causes each of these diseases.
congenital disorder of glycosylation (autosomal recessive): Limited. Congenital disorder of glycosylation (CDG) is a fast growing group of inborn errors of metabolism characterized by defective activity of enzymes that participate in glycosylation (modification of proteins and other macromolecules by adding and processing of oligosaccharide side chains).
Homologues: Orthologues: chimpanzee GFUS (99% identical), macaque GFUS (98% identical), dog GFUS (96% identical), mouse Gfus (94% identical), pig GFUS (93% identical), guinea pig GFUS (93% identical), rat Gfus (82% identical), tropical clawed frog gfus (81% identical), zebrafish gfus.1 (74% identical), zebrafish gfus.3 (72% identical), zebrafish gfus.2 (69% identical), Caenorhabditis elegans ger-1 (64% identical), and 1 more. Paralogues in human: SDR42E1 (17% identical), NSDHL (17% identical), UXS1 (17% identical), GALE (16% identical), HSD3B2 (16% identical), HSD3B7 (16% identical), HSD3B1 (16% identical), TGDS (16% identical), SDR42E2 (16% identical), GMDS (14% identical).
Diseases named in the same sentence as GFUS in open-access papers:
GFUS is named in the same sentence as 34 diseases in open-access papers, as found by Europe PMC text mining. Sharing a sentence is not in itself a finding about the gene and the disease. The quoted sentences say what the papers report.
colitis (3 papers, 2020 to 2022). Inflammation of the colon. "Understanding how these sugars are transported and utilized becomes especially important since various diseases/disorders (LADII, GFUS-CDG, SLC35A2-CDG, PGM1-CDG, colitis, various cancers) are already using or exploring “monosaccharide therapy”." (PMID 36423686, 2022).
viral infection (2 papers, 2020 to 2021). "Herein, the candidate genes PARP10, EXOSC4, GFUS and EEF1D, involved in various viral infections, were identified." (PMID 33255903, 2020).
congenital disorder of glycosylation (1 paper, 2021). "A novel type of congenital disorder of glycosylation (CDG) was identified in a child carrying biallelic variants in GDP‐L‐fucose synthase (GFUS)." (PMID 34468083, 2021).
congenital myasthenic syndrome (1 paper, 2023). Congenital myasthenic syndrome (CMS) is a group of genetic disorders of impaired neuromuscular transmission at the motor endplate characterized by fatigable muscle weakness. "Some examples of other (including multiple) glycosylation pathway defects discovered in the last five years are ATP6VI1-, GO7- (Congenital myasthenic syndrome), GET4-, GFUS- and GNPNAT1-CDG, and most recently CAMLG-CDG." (PMID 37858231, 2023).
GFUS also shares sentences with these, for which no sentence is quoted: tumor (11 papers); cancer (10); breast carcinoma (7); colorectal cancer (4); esophageal squamous cell carcinoma (3); adenocarcinoma (2); esophageal cancer (2); head and neck cancer (2); lung carcinoma (2); Anxiety (1); bipolar disorder (1); colon adenocarcinoma (1); colon cancer (1); Crohn disease (1); depression (1); glioma (1); Hepatitis (1); hepatocellular carcinoma (1); hypopharyngeal cancer (1); infection (1); laryngeal carcinoma (1); leukocyte adhesion deficiency (1); liver cancer (1); lung adenocarcinoma (1); lung squamous cell carcinoma (1); osteonecrosis (1); ovarian carcinoma (1); rectal cancer (1); schizophrenia (1); tongue cancer (1).